TREM2 (triggering receptor expressed on myeloid cells 2)
Diseases named in the same sentence as TREM2 in open-access papers (continued):
Sharing a sentence is not in itself a finding about the gene and the disease.
Hypercholesterolemia (14 papers, 2019 to 2025). An increased concentration of cholesterol in the blood. "TREM2 deficiency in this group of patients can lead to systemic hypercholesterolemia, body fat accumulation, and glucose intolerance." (PMID 39516356, 2024). "TREM2 deletion abrogated macrophage recruitment to enlarged adipocytes and caused massive adipocyte hypertrophy, systemic hypercholesterolemia, inflammation, and glucose intolerance, indicating the protective role of TREM2+ macrophages." (PMID 33763066, 2021). "To further assess the implications of Trem2 KO in vivo, we generated hypercholesterolemia and AngII induced AAA in Trem2 KO and WT mice." (PMID 41058009, 2025). "In response to d-flow under hypercholesterolemia, all MΦ clusters significantly accumulated, most notably MΦ3 and MΦ4 that highly expressed the markers of foam cells (Trem2, Lgals3, Gpnmb, Spp1, Lpl, and Fabp5)." (PMID 40092444, 2025). "Primary functions of TREM2+ LAMs include lipid uptake and tissue homeostasis, and genetic deletion of TREM2 leads to adipocyte hypertrophy and systemic hypercholesterolemia." (PMID 38426622, 2024). "Considering the lipid homeostasis-maintaining role of LAMs, it is possible that Trem2 prevents hypercholesterolemia by maintaining lipid homeostasis in adipose tissue." (PMID 35658903, 2022). "Trem2-expressing macrophages appear in obese adipose tissue and the genetic deletion of Trem2 in mice leads to adipocyte hypertrophy, hypercholesterolemia, and glucose intolerance." (PMID 31614590, 2019). "As hypercholesterolemia is a common sequela of cholestasis, the TREM2+ LAM in our samples may arise in response to similar metabolic derangements." (PMID 33411796, 2021). "Importantly, genetic ablation of Trem2 in obese mice suppressed the downstream molecular LAM program, resulting in adipocyte hypertrophy, systemic hypercholesterolemia, body fat accumulation and glucose intolerance, providing a new perspective on the function of Trem2 in metabolic disease." (PMID 40494889, 2025). "Targeting the TREM2 molecular pathway may be an important therapeutic target to re-program hepatic macrophages to an immune regulatory phenotype and reduce the consequences of hypercholesterolemia in cholestasis." (PMID 33411796, 2021). "Genetic ablation of Trem2 in mice globally inhibited the downstream molecular LAM program, leading to systemic hypercholesterolemia, body fat accumulation, and glucose intolerance." (PMID 39516356, 2024). "Interestingly, TREM2 deletion has been shown to cause weight gain, hypercholesterolemia, and glucose intolerance in mice due to the loss of LAM function, lipid uptake, and storage, indicating that Trem2+ LAM cells may be key in the mitigation of metabolic disruption in the AT." (PMID 37720534, 2023).
liver cirrhosis (14 papers, 2019 to 2025). "For example, TREM2+ CD9+ scar-associated macrophages can be observed in human liver cirrhosis exhibiting a profibrogenic gene signature 119, while TREM2-expressing macrophages have been identified in the circumstance of liver cancer." (PMID 39990657, 2025). "In liver cirrhosis or fatty liver, Trem2 is regarded as a pro-fibrotic marker associated with scar formation." (PMID 36982629, 2023). "In liver disorders, a TREM2+CD9+ subset of monocyte-derived macrophages (also referred to as “scar-associated” macrophages) expands during liver cirrhosis and contributes to pathogenesis." (PMID 35746551, 2022). "Those genes of MoMF cluster 02 were found to be expressed by resident liver KC and mature TREM2+ MoMF according to previously published scRNA-Seq data from liver cirrhosis and controls." (PMID 38638443, 2024). "The TREM2+CD9+ subset of macrophages that differentiate from circulating monocytes expands during liver cirrhosis and contributes to fibrosis." (PMID 35359989, 2022). "Similarly, in liver cirrhosis, a distinct population of CD9‐positive, TREM2‐positive macrophages, termed scar‐associated macrophages (SAMacs), also exhibits high levels of SPP1 expression." (PMID 40047497, 2025). "Two recent studies reveal that a novel profibrotic macrophage subset differentiated from circulating monocytes, CD9+TREM2+ macrophage, is significantly increased in patients with liver cirrhosis and plays a key role in activating HSCs at least via releasing TGF-β." (PMID 37415134, 2023). "Seven macrophage subsets were identified in the tissues of patients with liver cirrhosis, including Kupffer cells (resident macrophages in liver) and CD9+ triggering receptor expressed on myeloid cells 2 (TREM2)+ macrophages." (PMID 35773269, 2022).
prostate carcinoma (14 papers, 2022 to 2025). A carcinoma that arises from epithelial cells of the prostate gland. "They discovered that APOE secreted by prostate tumor cells induces the senescence of TREM2 + immunosuppressive neutrophils, which are associated with poor prognosis in prostate cancer patients." (PMID 41343534, 2025). "A recent paper suggested that APOE, secreted from prostate cancer cells, can bind to TREM2 on neutrophils and drive them towards a senescent phenotype that promotes tumor progression." (PMID 40523023, 2025). "Neutrophils and NK cells are the key components of the innate immune system, and prior studies have shown that prostate cancer cells induce senescence in TREM2+ immunosuppressive neutrophils by secreting APOE." (PMID 40242752, 2025). "Drawing on this, single cell and mechanistic studies in prostate cancer highlight and AR+/TREM2+ inhibitory TAM state that becomes more prevalent in mPCa, and particularly in bone metastases." (PMID 41488638, 2025). "A previous study has shown that prostate cancer cells promote the senescence of TREM2 + immunosuppressive neutrophils by secreting APOE, which exerts immunosuppressive and tumor-promoting effects." (PMID 37664173, 2023). "Genetic inactivation of the Apoe or Trem2 genes or the use of the histone deacetylase inhibitor romidepsin to specifically eliminate senescent neutrophils has been shown to effectively slow the progression of prostate cancer in mouse models." (PMID 40242752, 2025). "In metastatic foci, TREM2+ macrophages are specifically localized at the invasive edges of metastatic nodules, suggesting that TREM2 may be involved in prostate cancer metastasis." (PMID 40242752, 2025). "Moreover, alterations in metabolic processes, including dysregulated lipid metabolism, potentially mediated by upregulated Trem2, have also been identified in SPP1hi-TAMs, indicating a link to prostate cancer growth, invasiveness and therapeutic resistance." (PMID 39633050, 2025). "In advanced and castration resistant prostate cancer, spatial transcriptomics and imaging mass spectrometry flow cytometry showed co localization of TREM2 +/SPP1 + TAM with hypoxic and lipid rich tumor regions, adjacent blood vessels, and specific CAF subgroups." (PMID 41488638, 2025). "In prostate cancer models, PARPi-conditioned media drive chemotaxis of CCR2 positive monocytes and SPP1- or TREM2-biased TAM polarization during exposure to hypoxic and lipid-rich microenvironments, characteristics of the bone metastatic microenvironment." (PMID 41488638, 2025). "In prostate cancer, tumor-derived apolipoprotein E (APOE) binds to triggering receptor expressed on myeloid cells 2 (TREM2) on neutrophils, activating DAP12/SYK signaling." (PMID 40805288, 2025). "In prostate cancer, apolipoprotein E (APOE) in the TME binds to TREM2 on macrophages and promotes androgen receptor (AR) expression, which further upregulates the transcription of immune mediators such as IL-10, TGF-β1, IL-23A, and CCL2." (PMID 41417432, 2025). "As a result, AR, TREM2, and APOE are overexpressed in prostate cancer and correlate with poor prognosis The role of SPP1-expressing TAMs in tumor progression is under active investigation, and high SPP1 expression is linked to an unfavorable prognosis." (PMID 41417432, 2025). "In a mouse model of prostate cancer, tumor cell-released apolipoprotein E (APOE) interacts with triggering receptor expressed on myeloid cells 2 (TREM2) on neutrophils, triggering the senescence process in neutrophils." (PMID 38760815, 2024). "Additionally, in the tumor microenvironment of cribriform prostate cancer, there was found to be an increase in the number of C1QB+ TREM2+ APOE+ macrophages." (PMID 40242752, 2025). "Additionally, in prostate cancer, tumor-secreted APOE can bind to TREM2 on neutrophils, promoting neutrophil senescence." (PMID 39497214, 2024).
sarcoma (14 papers, 2021 to 2025). A usually aggressive malignant neoplasm of the soft tissue or bone. "The investigators first established that treatment with αPD-1 in TREM2 deficient mice led to further tumor control and regression in sarcoma and CRC models." (PMID 36119485, 2022). "We recently characterized the TREM2 contribution to the TAMs phenotype using the MCA1956 sarcoma model in Trem2-deficient mice." (PMID 35746551, 2022). "TREM2 deficiency has been shown to attenuate tumor growth, and combining TREM2 deficiency with PD-1 antibodies caused tumors to completely regress in a sarcoma mouse model." (PMID 35688160, 2022). "In murine models of sarcoma and CRC, TREM2 deficiency or TREM2 blockade in combination with PD-Ll blockade contributed to increased CD8 T cell activation and further limited tumor growth." (PMID 37492581, 2023). "Mice treated with the anti-TREM2 mAb displayed reduced tumor growth in the MCA sarcoma model and TME that partially resembled the TREM2 knockout condition." (PMID 35746551, 2022). "In mouse models of sarcoma, colorectal, breast, and gynecological cancers, TREM2 deletion or blockade with a monoclonal antibody has been shown to reduce tumor growth, enhance antitumor CD8+ T cell responses, including the effectiveness of anti-PD–1 treatment, and modified the TAM landscape." (PMID 38972873, 2024).
Cirrhosis (13 papers, 2021 to 2026). A chronic disorder of the liver in which liver tissue becomes scarred and is partially replaced by regenerative nodules and fibrotic tissue resulting in loss of liver function. "Cirrhosis-enriched TREM2+CD9+ scar-associated macrophages, largely originating from circulating monocytes, contribute to matrix remodeling and immune suppression; anti-TREM2 therapy paired with ICIs restored cytotoxic T-cell activity in preclinical studies." (PMID 41488615, 2025). "Single-cell RNAseq analysis of liver cells from NASH and cirrhosis patients has identified the presence of TREM2+ disease-associated macrophages (DAMs) in the liver that display lower expression of metabolic genes." (PMID 38280848, 2024). "Third, we were only able to detect a small number of CD9+/TREM2+ macrophages, indicating that this population is more associated with cirrhosis, as have been shown before, rather than NASH." (PMID 35931712, 2022). "Serum TREM2 and TSP-2 show promise for differentiating cirrhosis from simple steatosis and for distinguishing MASH patients from healthy individuals, respectively." (PMID 40282358, 2025). "For example, it shows a new TREM2+CD9+ macrophage subpopulation in human cirrhosis, refines the definition of endothelial subsets, and proposes new therapeutic targets for cirrhosis." (PMID 36387424, 2022). "Whereas, humans and mice with NASH or cirrhosis have increased hepatic expression of Trem2 that correlates positively with AST and ALT levels, more Trem2-expressing macrophages are also found in atherosclerotic plaques." (PMID 35083304, 2021). "Additionally, the scar-associated macrophages (SAMs) differentiated by markers such as TREM2, CD9, SPP1, TNFSF12, and LGALS3 and PDGFRA+ myofibroblasts had an increased proportion in patients with cirrhosis." (PMID 39889710, 2025). "Finally, our scRNAseq analysis shows the presence of DAMs in the liver of NAFLD patients, which share the same phenotype, including expression of TREM2, CD9, GPNMB, MHCII (HLA-DRB1), C1QA, and CLEC10A, as those found in the livers of patients with NASH and cirrhosis." (PMID 38280848, 2024).
demyelinating disease (13 papers, 2013 to 2025). A broad group of disorders that affect the myelin sheaths that cover the neurons. "Since CRL is a demyelinating disease and TREM2 regulates the uptake and processing of myelin debris, it is important to understand how Trem2 deficiency affects myelin uptake and processing by Csf1r+/− phagocytes." (PMID 37626591, 2023). "Overall, these findings establish reciprocal links between APOE and TREM2 in many microglial functions in AD and demyelinating disorders." (PMID 36564824, 2022). "Overall, these conflicting studies will prompt further dissection of the role of TREM2 in myelin clearance and lipid metabolism as well as the possibility to harness TREM2 in the treatment of demyelinating diseases." (PMID 36564824, 2022). "Activation of DAP12 and TREM-2 plays an important role in demyelination disease in humans, and this led us to examine the possible role of this pathway in preterm brain injury, which is characterized by extensive white-matter injury." (PMID 25187205, 2014). "Additionally, in various demyelinating diseases, TREM2 has been shown to regulate microglial phagocytosis and cholesterol metabolism." (PMID 38649789, 2024). "Elucidating the role of TREM2 may open up new avenues for therapeutic intervention in demyelinating diseases of the central nervous system." (PMID 37013543, 2023). "These animal models may suggest a beneficial role of TREM2 in demyelinating diseases, and considering our data indicating TREM2/TYROBP as an orthologue CPZ/MS pathway, upregulation of TREM2/TYROBP may be also beneficial in MS." (PMID 30114292, 2018). "It is pertinent to note that TREM2 expression was reduced in hippocampus from AD patients compared to controls, although increased TREM2 expression has also been shown in AD-like mouse models and models of demyelinating disease." (PMID 28303091, 2017). "Two of these genes, TREM2 and DAP12, were among the most highly induced during MHV-induced demyelinating disease." (PMID 24058676, 2013). "Further studies will be needed to establish the role that myelin-regulating properties of TREM2 and microglia have in prion and other neurodegenerative diseases that are not typically considered primary demyelinating disorders." (PMID 40400621, 2025).
ovarian carcinoma (13 papers, 2019 to 2026). A malignant neoplasm originating from the surface ovarian epithelium. "Preclinical studies have demonstrated that TREM2 blockade enhances the efficacy of ICIs, delays tumor progression, and promotes a favorable immune landscape in ovarian cancer." (PMID 40330466, 2025). "TREM2 protein is primarily expressed on TAMs compared to other analyzed myeloid populations, and of all the analyzed markers, ovarian cancer is most enriched in TREM2 and TAMs." (PMID 39003350, 2024). "The TREM2 as a tumor driver is usually overexpressed in numerous carcinoma including gastric, hepatic, and ovarian carcinoma." (PMID 36741909, 2023). "Histological analysis showed that TREM2 expression strongly correlated with disease stage in human ovarian cancer." (PMID 35746551, 2022). "Targeting TREM2 on TAMs was shown to enhance the efficacy of immunotherapy for ovarian cancer." (PMID 37563723, 2023). "However, anti-TREM2 mAbs were demonstrated in preclinical ovarian cancer models to deplete TAMs, enhance intratumoral CD8+ T cell activation, and reverse anti-PD-1 treatment resistance." (PMID 37508575, 2023). "Furthermore, TREM2 deficiency and anti-TREM2 monoclonal antibody treatment reportedly inhibit tumor growth in mice with CRC and ovarian cancer." (PMID 37563723, 2023). "Interestingly, ovarian cancer emerged as the tumor type having the highest TREM2 expression (above 1000 geometric mean fluorescent intensity), combined with TAM frequency (above 40% of the CD45+ infiltrating cells)." (PMID 35746551, 2022). "Similarly, studies have shown that the proportion of TREM2+ TAMs is significantly higher than that in other types of cancer and exhibits a notable correlation with the disease stage and poor prognosis of patients with ovarian cancer." (PMID 40242752, 2025). "Given the intratumoral heterogeneity of TAM polarization in ovarian cancer, a strategic combination of macrophage-targeted therapies, such as CSF1R and TREM2 inhibitors, with immunotherapies holds promise for improving clinical outcomes." (PMID 40330466, 2025). "These macrophages express higher levels of M2 markers, such as mannose receptor (MR) and triggering receptor expressed on myeloid cells 2 (Trem2), compared to macrophages stimulated by non-resistant ovarian cancer cells." (PMID 40330466, 2025).
Cerebral ischemia (12 papers, 2013 to 2024). Restriction of arterial blood supply to the brain associated with insufficient oxygenation to support the metabolic requirements of the tissue. "S100a8 and S100a9, the 11th most upregulated transcript in Trem2−/− mice in our data set, have been shown to play a role focal cerebral ischemia, with a deficiency in both transcripts resulting in diminished disease." (PMID 29040522, 2018). "Cerebral ischemia is associated with massive necrotic cell death that could potentially influence TREM2 signaling via release of reactive oxygen species, as in the case of bacterial stimuli." (PMID 23301011, 2013). "Increasing evidence has shown that upregulation of TREM2 results in strong neuroprotective effects by alleviating neuroinflammation in experimental cerebral ischemia." (PMID 32466767, 2020). "A previous study reported that the expression of TREM2 was upregulated as early as 6 h and peaked at approximately 72 h in a rat model of cerebral ischemia." (PMID 32466767, 2020). "Our study demonstrated that TREM2 protects against cerebral ischemia/reperfusion injury through the aspect of post-ischemic inflammatory response and neuronal apoptosis." (PMID 28592261, 2017). "Another study attempting to elucidate the mechanism of action of acupuncture therapy in improving cerebral ischemia showed that TREM2 could be a potential target in EA treatment for attenuating inflammatory injury following cerebral ischemia/reperfusion." (PMID 32952550, 2020). "The objective of the current study was to define the expression of MANF and TREM2 after focal cerebral ischemia and to investigate whether administration of DHA affects MANF and TREM2 expression and neurogenesis and provides additional neuroprotection." (PMID 32757264, 2020). "Conversely, acute brain injury-induced increases in TREM2 expression in microglia suggests that TREM2 may contribute to neurotrophic roles after brain ischemia and this may impart a long term neurological benefit in functional recovery." (PMID 24987367, 2014). "TREM2 and the chemokine receptors induced by TREM2 stimulation might have different functions in cerebral ischemia." (PMID 23301011, 2013). "In addition, previous experimental studies suggested a neuroprotective role of TREM2 activation or up-regulation after cerebral ischemia/reperfusion injury, while sTREM2 might inhibit the beneficial function of TREM2 through acting as a decoy receptor and competitively binding the ligands of TREM2." (PMID 35414082, 2022).